TNF (tumor necrosis factor)
Diseases named in the same sentence as TNF in open-access papers (continued):
Sharing a sentence is not in itself a finding about the gene and the disease.
melanoma (continued). "Accordingly, we used α2 macroglobulin, an inhibitor of all classes of endoproteases, to examine its effect on control and TNF-α stimulated HBL melanoma cells." (PMID 12966436, 2003). "More specifically for melanoma, TNF-α has been reported to upregulate the expression of integrin subunits and the interaction of human melanoma cells with ECM substrates." (PMID 12966436, 2003). "α-Melanocyte-simulating hormone can inhibit TNF-α-stimulated NF-κB activity in human melanocytes, melanoma cells and keratinocytes." (PMID 14612916, 2003). "More specifically, we have recently reported that tumour necrosis factor alpha (TNF-α) increases melanoma cell attachment to extracellular matrix (ECM) substrates and invasion through fibronectin." (PMID 12966436, 2003). "The data we now present and the first reports of IHP in melanoma and sarcoma liver metastases strongly indicate that in these patients TNF-α has therapeutic potential in IHP." (PMID 12610519, 2003). "We also found α-MSH to reduce TNF-α-stimulated NF-κB activity (and oxidative stress) in keratinocyte and melanoma lines, suggesting protection of the epidermis from inflammatory and oxidative stresses." (PMID 14612916, 2003). "In the current study, we extend our investigations into the role of inflammation in melanoma invasion by studying the effects of TNF-α on melanoma cell migration and degradative enzyme activity." (PMID 12966436, 2003). "We examined the effect of TNF-α on melanoma expression/activation of type IV gelatinases matrix metalloproteinases 2 and 9 (MMPs -2 and -9) and general proteolytic enzymes." (PMID 12966436, 2003). "We recently reported that TNF-α upregulated integrin expression in a human melanoma cell line and also increased the ability of cells to bind to substrates and to invade through fibronectin." (PMID 12966436, 2003). "Isolated perfusion of the extremities with high-dose tumour necrosis factor α (TNF-α) plus melphalan leads to dramatic tumour response in patients with irresectable soft tissue sarcoma or multiple melanoma in transit metastases." (PMID 10027309, 1999). "Isolated limb perfusion with tumour necrosis factor alpha (TNF-alpha) and melphalan is well tolerated and highly effective in irresectable sarcoma and melanoma." (PMID 9166936, 1997). "Twelve patients undergoing IL-2 and flavone acetic acid (FAA) combination immunotherapy for advanced melanoma were studied throughout treatment for the induction of measurable levels of bioactive TNF, GM-CSF and IL-6 in their serum." (PMID 8512819, 1993). "In addition, RSC-EXO reduced melanin production in α-MSH-stimulated B16F10 melanoma cells and suppressed the secretion of pro-inflammatory cytokines, including IL-1α, IL-6, and TNF-α, in LPS-stimulated RAW 264.7 macrophages." (PMID 42278464, 2026). "Analysis of the TCGA melanoma database showed that NOS1 expression is positively associated with several immune-related pathways, including the JAK-STAT, NF−κB, and TNF signaling pathways, suggesting a potential link between NOS1 activity and immune modulation." (PMID 41535256, 2026). "A deeper mechanistic understanding is needed, specifically, comprehensive assessment of inflammatory cytokines (IL-1β/6/8, TNF-α), ROS scavenging efficacy, and molecular profiling (qPCR/Western blot) will be incorporated to validate the anti-melanoma mechanisms of pYEEIE-RELNs-DOX." (PMID 40792208, 2025). "IL-6 and TNF-α enhance the survival and proliferation of melanoma cells." (PMID 40636453, 2025). "Interestingly, TNF blockade has been shown to overcome resistance to anti-PD-1 therapy in experimental melanoma, indicating potential cross-talk between TNF signaling and immune checkpoint pathways." (PMID 39998665, 2025). "However, a slightly increased relative risk was observed in tofacitinib-treated patients versus anti-TNF recipients for overall cancers (RR 1.4), melanoma (RR 1.47), and NMSC (RR 1.3)." (PMID 41228267, 2025).
melanoma (continued). "The role of TNF in the TME of malignant melanoma may be partly explained by its involvement in promoting the secretion of ROS-generating exosomes, which contribute to immune evasion." (PMID 40443670, 2025). "This prospective single-center study examined associations between serum cytokines—TNF-α, IL-2, and IL-10—and outcomes in stage IV non-small cell lung cancer (NSCLC, n = 43) and melanoma (n = 15) patients treated with Nivolumab at the Oncology Institute in Cluj-Napoca, Romania." (PMID 41020868, 2025). "The linear mixed-effects analysis examined TNF-α levels over time (baseline, 3 months, 6 months) across the two cancer types (melanoma vs. NSCLC) and included random intercepts for each participant and accounted for autocorrelation with an AR residual structure." (PMID 41020868, 2025). "•Murine melanoma supernatants induce production of NO, TNF-α, and IL-12." (PMID 40028040, 2025). "We demonstrate that, unlike the case for most other tumors, human lung adenocarcinoma and murine models of lung cancer are enriched for type 1 proinflammatory cytokines, such as IFN-γ and TNF-α, when compared with other malignancies, including melanoma, colon, and pancreatic cancers." (PMID 40553564, 2025). "TNF‐α also induced PD‐L1 overexpression through NF‐κB pathway in one canine melanoma cell line." (PMID 39789732, 2025). "5-aza-2′-deoxycytidine (5-Aza) induced melanoma cell apoptosis by upregulating tumor necrosis factor (TNF)-α, Fas ligand (FasL), and TNF-related apoptosis-inducing ligand (TRAIL), demonstrating anti-melanoma effects with minimal impact on normal human melanocytes in vitro." (PMID 40497999, 2025). "Moreover, TNF-α neutralization has been reported to prevent TNF-induced T-cell dysfunction and enhance responses to immune checkpoint inhibitors, particularly in preclinical models of melanoma and colorectal cancer." (PMID 40430573, 2025). "In the melanoma cohort, while baseline cytokine levels did not significantly predict survival, 3-month TNF-α levels were inversely associated with both survival and treatment response." (PMID 41020868, 2025). "Distinct patterns of immune activation and regulation are evident between cancer types, with melanoma patients generally exhibiting stronger pro-inflammatory responses (e.g., IL-2 and TNF-α elevations), while IL-10 dynamics suggest differential regulatory feedback." (PMID 41020868, 2025). "Copper can also have proinflammatory and prometastatic effects by promoting copper crosslinking with S100A4, a member of the S100 family of EF-hand calcium-binding proteins, which promotes nuclear factor-kappa B (NF-κB) activation and tumor necrosis factor-alpha (TNF-α) release in melanoma cells." (PMID 39970778, 2025). "More critically, these T cells secrete elevated levels of pro‐inflammatory cytokines such as IFN‐γ, TNF‐α, and IL‐6, which can support tumor‐promoting inflammation and alter the balance of immune‐stimulatory versus suppressive cues in the melanoma microenvironment." (PMID 40926366, 2025). "Additionally, elevated circulating levels of pro-inflammatory cytokines, such as tumor necrosis factor-alpha (TNF-α), interleukin (IL)-6, and C-reactive protein (CRP), have been linked to increased melanoma progression and poorer clinical outcomes." (PMID 40507159, 2025). "Additionally, anti-IL-20R2 treatment reduced the expression of IFNγ, GZMB, IL-2, and TNFα in Jurkat cells co-cultured with Vin-treated melanoma cells." (PMID 40866941, 2025). "Interestingly, the authors noted that, although the study was not able to evaluate risks for specific cancers, 19 patients in the anti-TNF-α group had received this therapy after a melanoma diagnosis, with 4 experiencing a recurrence." (PMID 40227584, 2025). "In melanoma and breast cancer mouse models, local ablation of lymphatic vessels results in peritumoral edema, with increased TAMs and other immunosuppressive cells, and high expression of inflammatory cytokines, e.g., TNF-α, IFN-γ, and IL1-β." (PMID 41511312, 2025).
melanoma (continued). "Among the melanoma cell lines, WM1366 cells exhibited the highest scores across multiple inflammation-associated pathways, particularly those associated with interferon signaling, cytotoxicity, chemokine signaling, tissue stress response, and TNF signaling." (PMID 41301529, 2025). "Melanoma-derived TNF displays dual functionality, acting as both a cytokine and growth factor by transferring to nearby melanoma cells via paracrine or juxtacrine routes, thereby activating NF-κB–mediated survival pathways, akin to IL-15 and IL-10 receptor signaling." (PMID 40443670, 2025). "TNF inhibitors, which were among the first biologics widely adopted for IBD, have been examined for increased risk of melanoma and NMSC, but studies have often been limited by confounding factors such as prior or concurrent thiopurine use and insufficient statistical power." (PMID 40427207, 2025). "Pharmacological inhibition of either IRE1α or NF-κB by STF-083010/ MKC8866 and BAY-11-7085 respectively could significantly suppress TG or HA15-induced increased transcription and secretion of both IL-6 and TNF-α in both A2058 and A375 melanoma cell lines." (PMID 38291473, 2024). "Furthermore, treatment with Eliglustat, a GCS inhibitor, inhibits TNF-induced melanoma cell dedifferentiation." (PMID 39136013, 2024). "Similarly, CSPG4 expression was also shown to confer resistance of melanoma cells to TNFα, doxorubicin and cisplatin treatment, most likely through activation of α3β1 integrin/PI3K signalling, which promotes cell survival." (PMID 39409881, 2024). "In addition, TNF-α stimulates the secretion of IL-8 by NF-κB activation, and its effects on melanoma growth and metastasis have been extensively reviewed in previous literature." (PMID 38656555, 2024). "Whether TNF blockade affects the anti-melanoma immune response triggered by immunotherapies in patients remains to be determined." (PMID 39136013, 2024). "PAF also promotes the production of immunosuppressive cytokines such as IL-10 and TGF-β while inhibiting the release of pro-inflammatory cytokines such as TNFα and interferon-gamma, allowing melanoma cells to evade immune surveillance and promoting tumor progression." (PMID 38791873, 2024). "However, in a study of melanoma, there was a decrease in serum levels of TNFα in patients with CRs, PRs, and SD." (PMID 38333710, 2024). "In addition, ROS are associated with various skin diseases such as eczema, contact dermatitis, melanoma, and skin cancer; therefore, suppressing TNF-α-induced ROS secretion is an important factor in preventing skin aging and disease." (PMID 38732481, 2024). "However, Kainulainen and colleagues recently described a protumor M1 macrophage subtype in melanoma, accentuating invasive melanoma cells by upregulating the TNFα signaling via NFκB in tumor cells." (PMID 38329386, 2024). "Furthermore, during the metastasis of B16F-10 melanoma cells in mice, compound 4 dramatically reduced the serum levels of proinflammatory cytokines such IL-1β, IL-6, TNF-α, and GM-CSF." (PMID 38732642, 2024). "Furthermore, it has been shown that high doses of recombinant TNFα are effective for treating melanoma and soft tissue sarcomas in isolated limb perfusion, where the agent penetrates local metastases but not the circulation." (PMID 38051374, 2024). "TNF was produced by 83% of primary melanomas and 57% of metastatic melanomas." (PMID 38474115, 2024). "Tumor Necrosis Factor (TNF) is known to be a key factor in melanoma dedifferentiation." (PMID 39136013, 2024). "In addition, NK cells, CD8 + T cells, and T helper cells secrete cytokines like IFNγ, tumor necrosis factor (TNF), and IL-2, preventing tumor growth and angiogenesis in a melanoma and a pancreatic cancer mouse model." (PMID 38419052, 2024). "Consequently, suppression of TNFα-signaling in melanoma allografts enhanced the efficacy of targeted therapy." (PMID 38942020, 2024).
melanoma (continued). "Higher expression of Th1-associated genes, such as tumor necrosis factor-alpha (TNF-α) and IL-2, was detected in 20 primary melanoma tumors that spontaneously regressed, indicating activation of the host antitumor immune response, compared with non-regressing tumors." (PMID 39273452, 2024). "sphingosine kinase 1 (SK1) and S1P are key players of TNF signaling in melanoma cells." (PMID 39136013, 2024). "KEGG pathway analysis using the 139 upregulated genes showed that cell cycle, AKT signalling pathway, MAPK signalling pathway, JAK‐STAT signalling pathway, TNF signalling pathway, and cytokine–cytokine receptor interaction were significantly upregulated in melanoma cells." (PMID 39496484, 2024). "Altogether, our study highlights for the first time that ceramide metabolism alterations contribute to TNF-induced melanoma cell dedifferentiation and opens new avenues for developing original therapeutic strategies aiming at reducing melanoma progression and resistance to therapies." (PMID 39136013, 2024). "Concerns have been raised that some agents, including TNF-alpha inhibitors (TNFi), may impair the anti-tumor immune response; however, investigations in melanoma murine models suggest TNF inhibition may actually augment anti-tumor immunity." (PMID 39737191, 2024). "We treated various cell types, including Huh-7 (hepatoma), J774A.1 (macrophage), B16F10 (melanoma), and primary mouse splenocytes, with different cell death inducers such as staurosporine (apoptosis), rapamycin (autophagy), erastin (ferroptosis), TNF-α (necroptosis), and nigericin (pyroptosis)." (PMID 39513885, 2024). "Thus, TNF-induced changes in ceramide metabolism likely contribute to melanoma dedifferentiation and aggressiveness." (PMID 39136013, 2024). "In addition, whereas the antitumor cytokines, like IFN-γ and TNF-α, in melanoma tissues increased, both IL-4 and IL-10 (pro-tumor cytokines) levels decreased at the end of the indicated treatment." (PMID 38491004, 2024). "Additionally, Ahnak’s role in regulating melanoma metastasis to lung epithelial cells via PCSK9 expression has been identified, where PCSK9 acts as an inhibitor of TNF α-mediated apoptosis, thus promoting melanoma cell metastasis to the lungs." (PMID 38974243, 2024). "V. cinerea extract also significantly inhibited lung tumor formation (by 78.8%) in B16F-10 melanoma cells by suppressing the production and expression of proinflammatory cytokines such as TNF-α, IL-1β, IL-6, and granulocyte-macrophage colony-stimulating factor (GM-CSF)." (PMID 38732642, 2024). "As changes in sphingolipid metabolism contribute to TNF-induced melanoma dedifferentiation, we hypothesized that some circulating sphingolipids may constitute biomarkers to predict resistance to immunotherapy." (PMID 39136013, 2024). "DeRogatis similarly observed in a melanoma model that PSGL-1-deficient mice exhibited augmented infiltration of CD4+ and CD8+ T cells, accompanied by elevated production of anti-tumor factors such as IFN-γ and TNF-α, resulting in delayed tumor growth." (PMID 39617949, 2024). "An increase in cell surface PD-L1 upon TH1902 treatment of B16-F10 melanoma cells, in part potentially facilitated through TNFα-mediated autocrine regulation, provides the molecular rationale for combining TH1902 and anti-PD-L1 CPI strategies in order to bypass resistance mechanisms." (PMID 38482021, 2024). "Conversely, incubating melanoma cell lines in the presence of Fumonisin B1 (FB1), which inhibits de novo sphingolipid synthesis, partially prevented the loss of Melan-a expression upon TNF treatment." (PMID 39136013, 2024). "In order to decipher the potential crosstalk that may link TNFα/IL-6 inductions triggered by TH1902 to the increased levels of MHC-I and PD-L1, B16-F10 melanoma cells were treated with the indicated TNFα or IL-6 concentrations for 96 hours." (PMID 38482021, 2024).
melanoma (continued). "Thus, the definition of oncogene has been proposed for Cx43 in melanoma; however, in human melanoma cell lines, Cx43 overexpression mitigates melanoma growth and metastasis and facilitates TNFα-induced cell apoptosis." (PMID 38473275, 2024). "Furthermore, the activation of other signalling pathways such as the tumour necrosis factor alpha (TNF-α)/nuclear factor kappa B (NF-kB) pathway enhances melanoma cell growth, and contributes to the failure of chemotherapy treatment including BRAF inhibitors." (PMID 36678596, 2023). "Once the diagnosis of melanoma in IBD patients under anti-TNFα therapy is made, different options of management could be taken into account." (PMID 36672491, 2023). "Thus, IL-6, IL-10, and TNF-α have been significantly decreased, inhibiting the growth and migration of melanoma cells, suggesting the potential of the two compounds tested to be used as antitumor drugs targeting inflammatory cytokines." (PMID 36829966, 2023). "In addition, an increased incidence of melanoma and lymphoma has been observed in patients taking anti-TNF-α agents." (PMID 37248486, 2023). "Indeed, all tumor cell lines derived from melanoma patients abrogated IL-12p40/p70 and TNFα production by cDC2s upon R848." (PMID 36891308, 2023). "Major evidence applies to the incident cancer risk on immunosuppressed patients and it demonstrates an increased risk of lymphoma and nonmelanoma skin cancer (NMSC) in patients on treatments with thiopurines, while melanoma incidence is increased 1.32-fold in patients under TNFα inhibitors." (PMID 36672491, 2023). "The high transcriptional IL4I1 expression by MHCII+ CD163− TAMs in MeLiM pigs with regressing melanoma was unexpected, but may result from the enriched IFNγ, TNFα, IL12 and IL6 tumor microenvironment between R0 and R1 stages." (PMID 37526660, 2023). "Firstly, in patients with stage I of melanoma and active IBD or high risk of relapse, the choice to continue the anti-TNFα could be considered, alongside a close dermatological follow-up." (PMID 36672491, 2023). "Therefore, we pursued a mechanism of TNF expression in melanoma based on Sp1, Ets-1, and cJUN activity." (PMID 37043573, 2023). "Despite these limitations, available preliminary evidence (mostly referring to overall cancer or melanoma) does not support that blocking TNFα increases the risk of new/recurrent cancer in IBD patients with prior cancer." (PMID 37113615, 2023). "It has been shown in a mouse model of melanoma that treatment with anti-CTLA-4 antibody or interleukin 2 (IL-2) immunotherapy leads to persistent production of intratumoral tumor necrosis factor alpha (TNF-α) and T cell accumulation, which increases EZH2 expression." (PMID 37325482, 2023). "The hypothesis was that MDM2 and SURVIVIN may be involved in the chemoresistance mechanisms of TNF melanoma metastases, interfering with its cytotoxic effect and, in particular, direct toxicity mediated by apoptosis." (PMID 38138884, 2023). "Melanization related pathways, i.e., melanogenesis (ko04916) and melanoma (ko05218), and immune related pathways, e.g., TNF signaling pathway (ko04668), Toll-like receptor signaling pathway (ko04620), NF-kappa B signaling pathway (ko04064) and so on, were also detected significantly enriched." (PMID 38031026, 2023). "We noted that loss of IL-1β expression could also enhance LC residency across the melanoma backgrounds, supporting the potential TNF-α–independent activation of LC migration by IL-1β." (PMID 37043573, 2023). "Enhanced levels of IL-6, TNF-α, and IL-1b in melanoma can trigger an immune response." (PMID 37895833, 2023). "This could arise as a result of accumulation of the cytokine, which may be produced by melanoma cells at low level, or as a result of localized inflammation driven by infiltrating immune cells leading to widespread TNF-α production in the rest of the tumor." (PMID 37043573, 2023).